CD4 (CD4 molecule)
Diseases named in the same sentence as CD4 in open-access papers (continued):
Sharing a sentence is not in itself a finding about the gene and the disease.
AIDS (continued). "HIV-1 infection is characterized by chronic immune activation, a major cause of CD4 T-cell depletion and HIV/SIV-specific immunity dysfunction, and facilitating viral replication and progression to AIDS." (PMID 24497833, 2014). "Based on viral load at set point that correlated well with clinical course (time to the development of AIDS) and absolute levels of peripheral blood CD4+ T cells, we grouped rhesus macaques experimentally infected with SIVmac into “HVL” and “LVL” strata." (PMID 25506344, 2014). "The most accurate cutoff of the CD4/CD8 ratio for the detection of non-AIDS events in a sensitivity/specifity plot was 0.4, with a sensitivity of 0.83 and a specificity of 0.45." (PMID 24497929, 2014). "Compared with patients who died of AIDS, those who died from non-AIDS causes were older, were more likely to be IDUs, had higher baseline CD4 count and lower viral load, and were less likely to have AIDS prior to ART." (PMID 24771333, 2014). "Of the 1262 participants, 208 were categorized as having a definite indication to start HAART (Group A), including 99 (48%) due to a CD4 count below 200 cells/mm3, 99 (48%) due to severe symptoms, and 10 (5%) for an AIDS-defining condition." (PMID 24460764, 2014). "After controlling for age, gender, ART duration, nadir and proximal CD4 count, each 10% decrease in the CD4/CD8 ratio and each 10% increase in the CD8+ T cell counts were associated with 48% and 22% higher odds of serious non-AIDS events, respectively." (PMID 24831517, 2014). "The level of evidence of the individual benefit of ART in terms of mortality or progression to AIDS increases with decreasing CD4 cell count." (PMID 24942364, 2014). "It has long been postulated that HIV evolves broader cellular tropism from CD4+ T lymphocytes to macrophages and that this viral adaptation is necessary for progression to AIDS." (PMID 24465411, 2014). "The infection of CD4+ cells by HIV leads to the progressive destruction of CD4+ T lymphocytes and, after a severe reduction of CD4+ cells, to AIDS." (PMID 24896832, 2014). "The measurement of CD4+ T-cell (CD4) counts is a strong predictor of progression to AIDS and a means of monitoring antiviral therapy (ART)." (PMID 24505247, 2014). "Here the total CD4+T cell counts decline from a value of 800 cells/ μL to a value below 200 cells/ μL (AIDS) after approximately 9 years in line with the clinical course of untreated HIV infection with R5 tropic virus." (PMID 24945407, 2014). "For example, absolute CD4+ cell counts in HIV patients has been crucial for defining HIV/AIDS disease status and is part of the criteria for treatment decisions." (PMID 24982762, 2014). "The imbalance in the ROS seems to contribute to the progression of AIDS in different ways, including the apoptosis of CD4 cells and the functioning of other immune system components." (PMID 24899897, 2014). "Female sex, higher pretreatment CD4+ cell count and pretreatment AIDS defining illness decreased the odds of having a PI-based regimen prescribed." (PMID 24695533, 2014). "More recent meta-analyses of randomized clinical trials show that prediction of AIDS events and death by CD4 and HIV-1 RNA is unreliable for people on cART and unsuitable for comparing treatment regimens for long-term clinical efficacy." (PMID 24667813, 2014). "HIV infection is characterized by a progressive depletion of CD4+ T cells, a severe dysregulation of the immune system function and progression to AIDS." (PMID 25340778, 2014). "Countries are requested to report each year, the number of HIV diagnoses, AIDS diagnoses, CD4 cell + count (CD4 count) at diagnosis and number of HIV tests performed, to the ECDC through The European Surveillance System (TESSy)." (PMID 24659343, 2014). "The severity of ocular manifestations in HIV/AIDS with respect to visual impairment was higher in patients with low CD4-counts." (PMID 27355047, 2014).
AIDS (continued). "In fact, even beyond severe immunodeficiency, individuals with CD4 cell counts between 350–500 cells/mm3 were found to have a three times higher incidence rate of AIDS events than those with CD4 cell counts >500 cells/mm3." (PMID 24885790, 2014). "A total of 41.8% had a CD4 cell count <200 cells/μL, 9.5% presented clinical AIDS and 64.4% received antiretroviral medications." (PMID 25005803, 2014). "In conclusion, Ethiopian HIV/AIDS patients with low CD4+ cell counts had an extremely high occurrence of Cryptosporidium infection, even when they were on HAART." (PMID 24743521, 2014). "The best predictor for onset of AIDS is the percentage or absolute numbers of circulating CD4+ T cells in peripheral blood." (PMID 24828336, 2014). "CD4+ T lymphocyte (CD4) cell counts are the primary laboratory markers used to track the progression of HIV to AIDS; however, clinicians still debate the appropriate CD4 threshold at which to initiate HIV therapy." (PMID 24778646, 2014). "The CD4 Measurements Cohort included 803 CD4 measurements (mean age 49, 76% male, 8% experienced an AIDS-defining event)." (PMID 24866200, 2014). "HIV infects and depletes the body's immune cells (CD4+T cells), and if untreated results in Acquired Immunodeficiency Syndrome (AIDS) and mortality approximately 10 years after initial infection." (PMID 24945407, 2014). "Early γδ T cell activation was associated with CD4/CD8 T cell activation set-points, which predict AIDS progression." (PMID 25188438, 2014). "Patients were at an advanced AIDS stage with a median [IQR] CD4+ T cell count of 25 cells/mm3 and median [IQR] BMI of 17.3 kg/m2 [15.8–19.1]; 167 patients (31%) had a body weight ≥50 kg, including 27 (5%) patients weighing ≥60 kg." (PMID 24608960, 2014). "A key objective of combined antiretroviral therapy (cART) is to reach and maintain high CD4 cell counts to provide long-term protection against AIDS-defining opportunistic infections and malignancies, as well as other comorbidities." (PMID 25393990, 2014). "We observed that a low CD4/CD8 ratio is a predictor of serious non-AIDS events among treated individuals with ≥500 CD4+ T cells/mm3 in the Madrid-based cohort, with much of the association driven by the CD8 counts." (PMID 24831517, 2014). "The measurement of CD4+ T-cell (CD4) counts is a strong predictor of progression to Human Immunodeficiency Syndrome (AIDS), as well as a means of monitoring antiretroviral therapy (ART)." (PMID 24505247, 2014). "98.59% of the patients with CD4 less than 50 copies/μL are at AIDS stage versus 15.62% of the patients with CD4 counts between 100 and 199//μL who are also at AIDS stage." (PMID 25408764, 2014). "HIV-infected patients with CD4 counts ≤200 cells/μl suffering from AIDS and from IgE-mediated allergy were studied." (PMID 24896832, 2014). "AIDS, which is characterized by a decrease in the CD4 lymphocytes, is currently believed to be the main culprit of this apoptosis." (PMID 24899897, 2014). "Poor immune restoration (<500 CD4+ cells/μL) leads to increased morbidity and mortality from AIDS-related illnesses and also from non-AIDS related conditions." (PMID 24695533, 2014). "The 15 patients from CT/AIDS group developed focal cerebral toxoplasmosis since they had low CD4+ lymphocytes counts." (PMID 25352834, 2014). "More importantly, early γδ T cell activation was associated with CD4 and CD8 T cell activation set-points, which predict AIDS progression." (PMID 25188438, 2014). "Baseline characteristics significantly differed between the two groups; in particular, lower CD4 counts and higher frequency of AIDS events were observed in migrants vs natives." (PMID 25397513, 2014). "Five microRNAs (miRNAs) - miR-16, miR-146b-5p, miR-150, miR-191 and miR-223 in peripheral blood mononuclear cells (PBMCs) were earlier found to assign HIV/AIDS patients into groups with varying CD4 T cell counts and viral loads." (PMID 24828336, 2014).
AIDS (continued). "There was a median of 450/μL (IQR 275–522)CD4+ T lymphocytes at the last check before delivery (reported in 23 of the 29 pregnancies); all women with a previous AIDS-defining condition had > 200 CD4+/μL." (PMID 24885649, 2014). "For instance, individuals with HIV/AIDS need antiretroviral therapy (ART) when they meet specific CD4 count thresholds." (PMID 25243780, 2014). "Multivariate multilevel model of the changes in CD4 + T cells over time of patients living with HIV/AIDS, including separately smoking (Model 1) and illicit drug use (Model 2)." (PMID 24505247, 2014). "An absolute CD4 count at six months of <200 cells/ml (Model 1) was the strongest predictor of progression to new AIDS condition and death." (PMID 24594114, 2014). "We evaluate the likely clinical impact in terms of preservation of total CD4+T cells, as well as in terms of forestalment of AIDS." (PMID 24945407, 2014). "About 28% of patients were classified (Centers for Disease Control and Prevention) as being in the AIDS stage and had a median of 344 CD4 T lymphocytes, and the majority had a viral load below 50 copies (78%)." (PMID 25642197, 2014). "A 50-year-old AIDS patient with a CD4 T-cell count of 114/mm3 was admitted with cerebellar symptoms of left CN XI weakness, wide-based gait with left-sided dysmetria, abnormal heel-knee-shin test, and dysdiadochokinesia." (PMID 25093131, 2014). "Among well-treated individuals with high CD4 count, a low ratio was an independent predictor of serious non-AIDS events and mortality." (PMID 24831517, 2014). "Very little is known about the association between serum sodium concentrations, CD4+ cell counts, and the severity and mortality of HIV/AIDS patients." (PMID 25360785, 2014). "Among all enrolled patients, 35.8% had CD4 <200/mm3, 17.5% had VL >100,000 copies/ml, 42.8% had had an AIDS event and 47.8% had received more than 10 different antiretroviral drugs." (PMID 25397525, 2014). "In conclusion we have demonstrated that gene therapy employing entry/fusion inhibitors can achieve substantial clinical impact in terms of long-term preservation of total CD4+T cells counts and forestalment of AIDS." (PMID 24945407, 2014). "The purpose of this study was to determine the pattern of ocular manifestations of HIV/AIDS and their correlation with CD4-count in a rural area of India." (PMID 27355047, 2014). "Perhaps due to the implementation of the national AIDS programs the proportion of patients with advanced HIV disease (CD4 count <200 cells/μl) has declined slightly since 2007." (PMID 24901790, 2014). "Previous data indicate that non-AIDS events are nowadays important contributors to HIV associated morbidity and mortality and that current CD4 is also a predictor of these events." (PMID 24498036, 2014). "Chronic immune activation (IA) is considered as the driving force of CD4+ T cell depletion and AIDS." (PMID 24991927, 2014). "The decreasing incidence rate of AIDS-related events over time confirms the improvements in HIV care as this finding is accompanied by a higher percentage of individuals with CD4 cell counts >500 cells/mm3 and undetectable plasma HIV RNAs." (PMID 24885790, 2014). "It is important to keep or recover an adequate CD4 T cell count as AIDS-related morbidity in HIV-infected patients increase significantly at counts below 750/mm3." (PMID 24465584, 2014). "For example, a study among newly diagnosed HIV-positive patients in Thailand found that 40% of the patients were unaware of their HIV serostatus, 50% of them presented with clinical AIDS and the median CD4 cell count at diagnosis was 260 cells/mm3." (PMID 24598459, 2014). "We defined late presentation as an initial CD4 count <350 cells/mm3 or presence of AIDS-defining disease at time of HIV diagnosis." (PMID 25397440, 2014).
AIDS (continued). "The contrasting OPTIMA cohort consisted of patients with clinically advanced AIDS, median CD4 count = 119 cells/mm3, highly treatment experienced, failing current treatment and having few effective anti-retroviral treatment options." (PMID 24667813, 2014). "LP were defined as patients presenting with CD4 T-cell count below 350 cells/mm3 or with an AIDS defining event." (PMID 25397441, 2014). "For example, depending on the organization of HIV/AIDS services, there are often several points at which an individual completes a CD4 evaluation: during testing, once initially enrolled in care, or upon initiating treatment." (PMID 25535408, 2014). "Factors significantly associated with the risk of developing an AIDS-defining event on cART on adjusted analyses were low body mass index below 16 kg/m2, WHO clinical stages 3 or 4 at baseline and CD4 strata below 200 cells/mm3 at initiation of therapy." (PMID 25340766, 2014). "We observed that both the CD4/CD8 ratio and CD8 count independently predicted the risk of non-AIDS events, with the coefficient of the CD4/CD8 ratio significantly higher." (PMID 24831517, 2014). "A large proportion of HIV-infected people still present for care with low CD4 cell count or with an AIDS-defining event (ADE) at first diagnosis of HIV infection." (PMID 24587081, 2014). "In 2004, the ARV became available for all patients with CD4 counts below 200 cells/mm3 or those presenting AIDS-defining illness." (PMID 24763617, 2014). "Chronic immune activation is a characteristic of HIV infection and a key contributor to CD4 T-cell depletion and progression to AIDS." (PMID 24497833, 2014). "Several studies analysed the association between the expression of CCR5 and disease progression, such as time to AIDS, CD4 cell decline or serum viral load levels." (PMID 25495598, 2014). "The critical role of CD4+ T cell help in proper immune functioning is most clearly demonstrated in HIV+ patients suffering from AIDS." (PMID 25119341, 2014). "Upon administration of effective ART, peripheral CD4+ T cell counts increase and there is a significant decrease in AIDS-related clinical conditions, but alterations in the distribution and function of certain T cell subpopulations persist." (PMID 24465619, 2014). "Median age was 35 years, males accounted for 70% of patients, median CD4 was 147 cells/mm3, and 41% had AIDS prior to HAART initiation." (PMID 25221931, 2014). "A change in HIV-1 bias for binding to CXCR4 over CCR5 precedes AIDS development and the decline in CD4 cell number." (PMID 25196285, 2014). "With services provided by CBOs and health facilities, in accordance with the national new HIV/AIDS prevention and control approach of ‘Five expands, six strengthens’, coverage of CD4 tests among PLHA increased by about 15%, reached nearly 86% in 2012." (PMID 25050797, 2014). "Overall, our patients had fairly advanced HIV disease, as shown by the median nadir of 189 CD4+ cells/mm3 and by the fact that 42.8% had a previous AIDS defining illness." (PMID 24699873, 2014). "Apoptosis is one of the presumptive causes of CD4+ T cell depletion during HIV infection and progression to AIDS." (PMID 24886575, 2014). "Data from two regional cohort observational databases were analyzed for trends in median CD4 cell counts at ART initiation and the proportion of late ART initiation (CD4 cell counts <200 cells/mm3 or prior AIDS diagnosis)." (PMID 24598459, 2014). "Repeated administrations of TLR7 ligands in mice induce AIDS-like lymphopenia, with reduced CD4+ T cells, CD8+ T cells and B cells." (PMID 25077616, 2014). "The total NK cells count in patients with <300 CD4+ lymphocytes/mm3 was lower in AIDS-RL in comparison with the other groups, suggesting a poor prognosis as shown in low or high grade HIV-negative lymphomas." (PMID 25908934, 2014). "The result was consistent to the primary outcome of HIV infection in that the CD4+ cell counts continued to decline, thereby resulting in AIDS." (PMID 24816922, 2014).
AIDS (continued). "In the EuroSIDA study, a decrease in 1 g/dL of hemoglobin level augmented the hazard of death (HR = 1.57; 95% CI: 1.41-1.75), after controlling for demographic variables, antiretroviral treatment, AIDS, CD4 count and viral load." (PMID 25005803, 2014). "It has been shown that the likelihood of progressing to AIDS for subjects with baseline viral load (VL) around or lower than 10,000 copies/mL is dependent on baseline CD4+ T cell counts." (PMID 25187947, 2014). "This in turn leads to a higher decrease in the CD4+ T-cell count, which ultimately leads to AIDS and the terminal stage of the infection." (PMID 24899897, 2014). "People who were diagnosed with HIV in more recent years were more likely to have missing data for CD4 count or viral load at time of their AIDS diagnosis." (PMID 24587081, 2014). "Following the same strategy, a low CD4/CD8 ratio was a predictor of non-AIDS mortality (per quartile decrease; OR, 2.8; 95% CI, 1.5–5.3; for CD4/CD8 ratio <0.4; OR, 4.5; 95% CI, 1.7–11.8)." (PMID 24497929, 2014). "Increased activation and turnover of monocytes predict progression to AIDS in SIV-infected RMs even better than CD4+ T-cell number." (PMID 25356757, 2014). "Median CD4 count was lower in patients with an AIDS diagnosis (58/mm3) or another infection (88/mm3) than in patients with other diseases (154/mm3)." (PMID 24713375, 2014). "At the initiation of ART, around 60% of patients had already had AIDS defined illness and the median CD4 cell count was as low as 50 cells/ml (Interquartile range, IQR 17-118)." (PMID 25361850, 2014). "The coverage of HIV testing and HIV detection rate among men who have sex with men, the median CD4 counts among local HIV/AIDS cases, through services by community-based organizations (CBOs), 2008 to 2012,Nanjing, China." (PMID 25050797, 2014). "This was a retrospective study, which enrolled patients diagnosed with HIV/AIDS (CD4<200 cells/μl), who had detectable CMV viral load (VL) during their stay in an adult medical intensive care unit between 2009–2012." (PMID 24699683, 2014). "All documented infections by M. genavense have been in immunocompromised hosts, mainly AIDS patients with CD4 count below 50/μL in the pre-HAART era, except for one reported case of lymphadenitis in a healthy human." (PMID 24693456, 2014). "Patients in the LTFU cases also had higher CD4+ lymphocyte counts and were less likely to have an AIDS diagnosis or to have received antiretroviral therapy than the controls." (PMID 23922753, 2013). "In August 2011, the South African Department of Health increased the ART initiation threshold from CD4<200 to <350 cells/mm3 to help reduce AIDS-related deaths." (PMID 23383147, 2013). "An initial presentation with AIDS or a CD4 cell count below 200 cells/mm3 is now referred to as “advanced disease”, and an initial presentation with AIDS or a CD4 cell count below 350 cells/mm3 as “late HIV diagnosis”." (PMID 23331544, 2013). "Persons living with AIDS who have CD4 T-lymphocyte counts < 200 cells/mm3 are highly vulnerable to foodborne enteric infections with the potential for substantial morbidity and mortality." (PMID 24124447, 2013). "The primary outcome was HIV disease progression, defined as antiretroviral initiation, development of AIDS/opportunistic infection, or progression to CD4 count thresholds (≤200 or ≤350 cells/mm3)." (PMID 24164861, 2013). "Unfortunately, 61.46% of the HIV infectors in our study received a concurrent diagnosis of AIDS which was defined by a CD4+ T-cell count<200 cells/μL or by an AIDS-defining illness." (PMID 24376638, 2013). "The effect of higher viral load and lower CD4 T-cell count at set-point on progression to AIDS or death is difficult to study in the combination antiretroviral therapy (cART) era as these endpoints are hardly observed in effectively treated patients." (PMID 23724048, 2013).